COLGALT1 (collagen beta(1-O)galactosyltransferase 1)
Description:
Beta-galactosyltransferase that transfers beta-galactose to hydroxylysine residues of type I collagen. By acting on collagen glycosylation, facilitates the formation of collagen triple helix. Also involved in the biosynthesis of collagen type IV.
Synonyms: ColGalT 1; GLT25D1; FLJ22329; BSVD3
Tractability: Antibody: UniProt predicts a signal peptide or a membrane-spanning region. PROTAC: ubiquitination databases record sites on it; its protein half-life has been measured.
Target class: Enzyme; Transferase
Gene: Protein-coding gene on chromosome 19 (17,555,631 to 17,583,162, forward strand). Ensembl gene ENSG00000130309.
Subcellular location: Endoplasmic reticulum lumen
Subcellular location (Human Protein Atlas): Vesicles; Golgi apparatus
Pathways (Reactome):
Extracellular matrix organization: Collagen biosynthesis and modifying enzymes
Gene Ontology:
Molecular function: procollagen galactosyltransferase activity
Biological process: positive regulation of collagen fibril organization; protein O-linked glycosylation via galactose; collagen fibril organization
Cellular component: endoplasmic reticulum lumen; membrane
Genetic constraint (gnomAD): Loss-of-function variants: 44 observed, 55.39 expected, observed/expected ratio (o/e) 0.79, 90% interval 0.62 to 1.02. The upper end of that interval is the gene's LOEUF score, 1.02, which puts it in group 4 of 6, group 1 being the genes least tolerant of losing a copy. Missense variants: 777 observed, 792.89 expected, observed/expected ratio (o/e) 0.98, 90% interval 0.92 to 1.04. Synonymous variants: 342 observed, 318.17 expected, observed/expected ratio (o/e) 1.07, 90% interval 0.98 to 1.18.
Gene-disease validity (ClinGen):
ClinGen rates the evidence that COLGALT1 causes each of these diseases.
brain small vessel disease 3 (autosomal recessive): Moderate.
Homologues: Orthologues: chimpanzee COLGALT1 (99% identical), macaque COLGALT1 (99% identical), dog COLGALT1 (96% identical), pig COLGALT1 (96% identical), mouse Colgalt1 (91% identical), rat Colgalt1 (91% identical), guinea pig COLGALT1 (91% identical), Caenorhabditis elegans D2045.9 (31% identical). Paralogues in human: COLGALT2 (64% identical), CERCAM (53% identical), PLOD1 (22% identical), PLOD3 (21% identical), PLOD2 (20% identical).
Diseases named in the same sentence as COLGALT1 in open-access papers:
COLGALT1 is named in the same sentence as 25 diseases in open-access papers, as found by Europe PMC text mining. Sharing a sentence is not in itself a finding about the gene and the disease. The quoted sentences say what the papers report.
cerebral small vessel disease (3 papers, 2019 to 2024). Cerebral small vessel disease is the term currently used to pathological processes that affect the brain parenchymal circulation (arterioles, capillaries, and veins). "COLGALT1, located in 19p13.11, encodes collagen β (1-O) galactosyltransferase 1 (ColGalT1), and is associated with musculoskeletal defects, cerebral small vessel disease, and congenital porencephaly." (PMID 36979105, 2023). "Of note, a recent report described compound heterozygous mutations of COLGALT1 in two pediatric patients with cerebral small vessel disease." (PMID 31101663, 2019).
diabetes (3 papers, 2017 to 2023). "Although, bi-allelic variants of COLGALT1 have been associated with brain small vessel disease, to date there are no studies that have investigated its role in development of diabetes or cardiovascular complications that result as an outcome of long-standing metabolic syndrome." (PMID 36991398, 2023).
mammary tumor (2 papers, 2020 to 2021). "As a beta (1-O) galactosyl-transferase that modifies collagen, COLGALT1 is reported to be involved in the development of mammary tumor metastases." (PMID 32523950, 2020). "As previously reported, COLGALT1 is involved in the progression of mammary tumor metastases." (PMID 34131588, 2021).
osteosarcoma (2 papers, 2017 to 2020). A usually aggressive malignant bone-forming mesenchymal neoplasm, predominantly affecting adolescents and young adults. "The inactivation of COLGALT1 in osteosarcoma cells led to collagen type I accumulation, and cells with inactive COLGALT1 and COLGALT2 genes could not be grown, suggesting that osteosarcoma cell viability and proliferation are impaired by a complete loss of collagen glycosylation." (PMID 32523950, 2020).
congenital muscular dystrophy (1 paper, 2019). A muscular dystrophy that is characterized by diminished muscle tone (hypotonia), progressive muscle weakness and degeneration (atrophy), abnormally fixed joints, spinal rigidity, and delays in reaching motor milestones such as sitting or standing unassisted. "We hypothesize that the Colgalt1 mutant could serve as a model of a human connective tissue disorder and/or congenital muscular dystrophy or myopathy." (PMID 31101663, 2019).
glioblastoma (1 paper, 2022). The most malignant astrocytic tumor (WHO grade IV). "We noticed COLGALT1 is highly expressed in cholangio carcinoma (CHOL), glioblastoma (GBM), bladder urothelial carcinoma (BLCA), KIRC, etc. and down-regulated in Kidney Chromophobe (KICH) compared with corresponding normal samples from the TCGA data set." (PMID 35842702, 2022).
kidney tumor (1 paper, 2022). "Besides, through the ICGC and GEO databases (GSE6344), we found that COLGALT1 is also up-regulated in kidney tumor tissues." (PMID 35842702, 2022).
pulmonary fibrosis (1 paper, 2024). Chronic progressive interstitial lung disorder characterized by the replacement of the lung tissue by connective tissue, leading to progressive dyspnea, respiratory failure, or right heart failure. "The massive secretion of COLGALT1 in macrophages promoted the galactose modification of COL3A1, thus further aggravating the pulmonary fibrosis cascade." (PMID 39083563, 2024).
viral infection (1 paper, 2021). "Evidence compiled in miRTarBase indicates that miR-128-1-5p has 3 validated targets—AC1N1, AP2S1, COLGALT1—among the proteins changing after viral infection according to H2V database." (PMID 34198800, 2021).
tumor (5 papers, 2010 to 2024). "We found high protein expression of COLGALT1 is related to normal or tumor, male or female, different grades or stages." (PMID 35842702, 2022). "Based on immunohistochemical images from the HPA database, we noticed tumor tissues have a greater level of COLGALT1 protein expression than normal tissues." (PMID 35842702, 2022). "The expression of COLGALT1 was then compared in 72 pairs of samples including KIRC tissue and the para-cancerous tissue, and we found COLGALT1 is similarly up-regulated in tumour tissues." (PMID 35842702, 2022). "Using pancancer sequencing data from the TCGA database, we evaluated the expression of COLGALT1 in various tumour samples compared with normal samples." (PMID 35842702, 2022). "Interestingly, correlation analyses revealed an association between COLGALT1 and microsatellite instability (MSI), tumor mutational burden (TMB) and immunity (P < 0.001)." (PMID 35842702, 2022). "Furthermore, we employed another online tools of Sangerbox website to assess the relationships between COLGALT1 expression and tumor microenvironment in TCGA–KIRC data set." (PMID 35842702, 2022). "Therefore, differential expression of COLGALT1 might contribute to tumor immunotherapy." (PMID 35842702, 2022). "A visual check of the spatial distribution for three of the niche-DE genes (COLGALT1, COL4A1, and CTBP2), each in a separate patient sample, reveals that niche-DE gene expression are indeed enriched in regions of the tissue where fibroblasts and tumor cells colocalize." (PMID 38217002, 2024).
cancer (1 paper, 2022). A tumor composed of atypical neoplastic, often pleomorphic cells that invade other tissues. "According to the pan-cancer analysis of COLGALT1 and MSI, the differential expression of COLGALT1 is associated with MSI in STAD (p = 3.6e-05), COAD (p = 0.0083), BRCA (p = 0.0031), LUSC (p = 0.0069) and KIRC (p = 0.0027)." (PMID 35842702, 2022).
connective tissue disorder (1 paper, 2019). A disease involving the connective tissue. "We also suggest that it is likely that mutations of COLGALT1 would cause connective tissue disorders in humans, similar to the patient with a defect in PLOD3 expression whose phenotype included bone fragility and contractures." (PMID 31101663, 2019).
COLGALT1 also shares sentences with these, for which no sentence is quoted: COVID-19 (2 papers); aneurysm (1); autoimmune disease (1); cerebrovascular disease (1); diabetes retinopathy (1); gestational diabetes (1); Gould syndrome (1); hepatoma (1); metabolic syndrome (1); myopathy (1); nephrogenic diabetes insipidus (1); Obesity (1); Simpson-Golabi-Behmel syndrome (1).